NLRP3 (NLR family pyrin domain containing 3)
Diseases named in the same sentence as NLRP3 in open-access papers (continued):
Sharing a sentence is not in itself a finding about the gene and the disease.
pulmonary fibrosis (continued). "In SiO2-induced lung fibrosis, the CircPWWP2A/miR − 223–3p/ NLRP3 pathway has potential roles in the regulation of inflammation and fibrogenesis, hence highlighting its therapeutic significance." (PMID 38321530, 2024). "Targeting NOX4-derived ROS and disrupting the self-perpetuating loop between NOX4, ROS, and NLRP3 inflammasomes are potential strategies for intervening in the pathogenesis and progression of pulmonary fibrosis." (PMID 38166847, 2024). "PCSK9 inhibition or statin administration decreased NLRP3 production of respiratory epithelium and improved lung fibrosis in TGF-β1 overexpressing transgenic mice." (PMID 38762465, 2024). "CircPWWP2A is a profibrotic circRNA sponging miR − 223–3p, which has an inhibitory effect on NLRP3 to promote pulmonary fibrosis." (PMID 38321530, 2024). "Studies have also shown that NLRP3 inflammasome-mediated cell pyroptosis is closely related to idiopathic pulmonary fibrosis (IPF)." (PMID 38875245, 2024). "Overall, we highlight in this study the ability of the P2RX7/NLRP3/IL-18 pathway in immune cells to inhibit the onset of lung fibrosis by using a positive modulator of P2RX7 that acts selectively in an eATP-rich environment such as fibrotic lung." (PMID 38300690, 2024). "Overall, we show that the P2RX7/NLRP3/IL-18 axis in immune cells is required to limit lung fibrosis progression, highlighting the efficacy in targeting the immune system in this disease." (PMID 38300690, 2024). "In pulmonary fibrosis research, the activation of Nuclear Factor Kappa B (NF-κB)/NLRP3 signaling induces the upregulation of MMP2/9 expression." (PMID 38992615, 2024). "Joshi and colleagues have recently demonstrated the connection between plastin-2 and the NLRP3 inflammasome activation in macrophages using a mouse model of lung fibrosis." (PMID 39683940, 2024). "The NLRP3 inflammasome triggers interleukin-1β secretion, which directly affects fibroblast activation, proliferation, and migration, eventually leading to lung fibrosis." (PMID 36694200, 2023). "Previous studies have also shown that mtROS are closely related to the activation of NLRP3 inflammasome in postoperative cognitive dysfunction and pulmonary fibrosis." (PMID 37312196, 2023). "The results showed that BB was involved in the protective effect of lung fibrosis mice through NLRP3 and JNK/NF-κB signaling pathways." (PMID 36733844, 2023). "Previous studies have also shown that NLRP3 inflammasome is involved in fibrotic diseases, including idiopathic pulmonary fibrosis (IPF)." (PMID 36694200, 2023). "In contrast, the inhibition of the NLRP3 inflammasome via the administration of YVAD attenuated the increase in the p-FAK-to-FAK ratio in bleomycin-induced pulmonary fibrosis." (PMID 37958797, 2023). "We reported that the NLRP3 inflammasome canonical pathway is activated in lung epithelial cells in response to radiation-induced damage, contributing to pulmonary fibrosis by activating fibroblasts." (PMID 36694200, 2023). "The aim of this study is to investigate the mechanisms of the NLRP3 inflammasome and EndoMT in bleomycin-induced pulmonary fibrosis." (PMID 37958797, 2023). "In chronic lung diseases, NF-κB can induce the process of pulmonary fibrosis by mediating the up-regulation of NLRP3 or NOX4." (PMID 37858201, 2023). "IL-1β is a classical downstream effector molecule of NLRP3, and previous studies have demonstrated the role of IL-1β in pulmonary fibrosis." (PMID 36694200, 2023). "Our study aimed to investigate the role of the NLRP3 inflammasome in the regulation of EndoMT in pulmonary fibrosis." (PMID 37958797, 2023). "NLRP3-induced pyroptosis is exhibited in various clinical situations, such as acute lung injury, pulmonary fibrosis, and lung cancer." (PMID 37371919, 2023). "In the present study, the role of the NLRP3 inflammasome in the regulation of EndoMT in pulmonary fibrosis was demonstrated." (PMID 37958797, 2023).
pulmonary fibrosis (continued). "The mechanism by which NLRP3 contributes to the development of lung fibrosis begins with the activation of toll-like receptor (TLR) and NF-κB, providing a priming signal that induces the upregulation of pro-IL-1β and inflammasome components." (PMID 38003456, 2023). "In bleomycin-induced pulmonary fibrosis model, the activation of the NLRP3 inflammasome promotes the expression of TGF-β, resulting in EMT." (PMID 38082306, 2023). "Considering these findings, targeting the NLRP3 inflammasome pathway presents a potential therapeutic approach to reduce inflammation and halt the progression of lung fibrosis during respiratory system infections." (PMID 37686825, 2023). "The nucleotide-binding domain leucine-rich repeat-containing receptor, pyrin domain-containing-3 (NLRP3) inflammasome and endothelial-to-mesenchymal transition (EndoMT) were shown to be involved in the pathogenesis of pulmonary fibrosis." (PMID 37958797, 2023). "The activation of the NLRP3 inflammasome in alveolar epithelial cells promotes the differentiation of mesenchymal stem cells into myofibroblasts during the pulmonary fibrosis process." (PMID 37960237, 2023). "NLRP3 inflammasome activation is also observed in pulmonary fibrosis models induced by asbestos, silica and bleomycin, and pulmonary fibrosis is alleviated by the inhibition of NLRP3 inflammasome activation." (PMID 35596212, 2022). "Specifically, the EV miRNA let-7 from MenSCs remits pulmonary fibrosis by modulating cellular reactive oxygen species, mitochondrial DNA damage, and NLR family pyrin domain containing 3 (NLRP3) inflammasome activation." (PMID 35909143, 2022). "Age-dependent differences for NLRP3 inflammasome activation have been described in the literature and aged mice showed an enhanced NLRP3 inflammasome activation in alveolar macrophages, contributing to the development of pulmonary fibrosis." (PMID 36131923, 2022). "MCC950 has shown its protective property through inhibition of NLRP3 activation in silicon dioxide-induced pulmonary fibrosis through preventing macrophage-derived IL-1β excretion and then impeding myofibroblasts transition." (PMID 35974386, 2022). "This is shown by in vitro and in vivo models of mechanical ventilation-induced pulmonary fibrosis, which both exhibit NLRP3 activation." (PMID 35743263, 2022). "Recent studies have reported that Caspase-1 and NLRP3 levels in idiopathic pulmonary fibrosis and asthmatic patients are higher than those in healthy patients." (PMID 36432032, 2022). "In summary, our study initially confirmed ER stress-induced NLRP3 inflammasome activation in type II AECs, promoted cell pyroptosis, and ultimately exacerbated pulmonary fibrosis." (PMID 36033388, 2022). "Previous studies showed that increased ROS is also a classical mechanism that induces NLRP3 inflammasome activation playing important role in pulmonary fibrosis and EMT." (PMID 35596212, 2022). "Previous studies demonstrated that NecroX-5 suppressed the NLRP3 pathway, which contributes to lung fibrosis in mice." (PMID 35596212, 2022). "Lung fibrosis is exacerbated by Angiotensin (Ang) II via NLR family pyrin domain containing 3 (NLRP3) pathways." (PMID 36119644, 2022). "Collectively, these observations indicated elevations of ER stress and NLRP3 inflammasome activation in BLM-induced pulmonary fibrosis." (PMID 36033388, 2022). "NLRP3 inflammasome activation contributes to mechanical stretch induced EndMT and pulmonary fibrosis." (PMID 35250619, 2022). "We have previously identified NLRP3 as a potential raltegravir target in the context of lung fibrosis." (PMID 36350972, 2022). "A20, an anti-inflammatory protein which is also known as TNF-α-induced protein 3 (TNFAIP3), shows a protective role in pulmonary fibrosis and it was reported to reduce NLRP3-mediated cytokine secretion and pyroptosis in RA." (PMID 35974386, 2022).
pulmonary fibrosis (continued). "Non-physiological mechanical stretch stimulated excessive ATP release from the lung alveolar cells; ATP induced the release of IL-1β via activation of the NLRP3 inflammasome through P2 × 7R receptor binding and facilitated the progression of lung fibrosis." (PMID 35250619, 2022). "NLRP3 inhibitors have been developed to interfere with the NLRP3 machinery, and NLRP3-knockout has been investigated in different animal models of pulmonary fibrosis." (PMID 36248872, 2022). "NLRP3 inflammasome lead to pulmonary fibrosis through the IL-1β/IL-1Rs/MyD88/NF-κB signaling pathway." (PMID 34177893, 2021). "After isolation of mouse primary lung fibroblasts, BLM was added to the mouse primary lung fibroblasts, and it was found that NLRP3 inflammasome regulate IL-1β via miR-155, leading to lung fibrosis." (PMID 34177893, 2021). "In this study we demonstrated that AMs in pulmonary fibrosis secrete abundantly IL-1β following stimulation of the NLRP3 and AIM2 inflammasomes compared to healthy subjects." (PMID 34220810, 2021). "Anaerobic glycolysis and aerobic glycolysis are also thought to promote the formation of pulmonary fibrosis by activating NLRP3 or AIM2 to induce macrophage pyroptosis and by mediating the transcription of IL-1β through the HIF-α pathway, respectively." (PMID 34944017, 2021). "The role of oxidative stress in CNTs-induced lung fibrosis was demonstrated through the use of the antioxidant N-Acetyl Cysteine, which interfered with NLRP3 inflammasome activation and generation of pulmonary fibrosis in mice." (PMID 33804168, 2021). "Previous studies showed that activation of the NLRP3/caspase‐1 pathway contributed to the inflammatory response in the development of various diseases, including pulmonary fibrosis, airway inflammation, and chronic obstructive pulmonary diseases." (PMID 32996690, 2021). "To conclude, in the present study, we reported that a natural-derived scutellarin significantly ameliorated inflammation response and EMT process through NF-κB/NLRP3 signal pathway in BLM-induced pulmonary fibrosis." (PMID 33188176, 2020). "Then, we are the first to report that scutellarin inhibits the activation of NLRP3 in pulmonary fibrosis." (PMID 33188176, 2020). "Lycorine is effective at decreasing the a-SMA, fibronectin and collagen content in bleomycin-induced pulmonary fibrosis via inhibiting NLRP3 inflammasome activation and pyroptosis." (PMID 33390969, 2020). "Our study reported that scutellarin ameliorated pulmonary fibrosis through modulating NF-κB/NLRP3-mediated EMT and inflammatory response." (PMID 33188176, 2020). "The role of NLRP3 inflammasome has also been tested in other pulmonary fibrosis models including ventilator induced lung fibrosis, silica-induced fibrosis, and particular manner-induced fibrosis." (PMID 32121297, 2020). "Taken together, scutellarin delivered anti-inflammatory efficacy in pulmonary fibrosis through inhibiting BLM-induced NF-κB/NLRP3 signaling, and overexpression of NLRP3 partly eliminated the function of scutellarin." (PMID 33188176, 2020). "Several studies have demonstrated a role for the NLRP3 inflammasome and its regulated cytokines in lung fibrosis in experimental lung fibrosis." (PMID 32121297, 2020). "Phagocytosed silica particles cannot be digested in phago-lysosomes, which induces lysosomal stress and activates NLRP3 inflammasomes, followed by progressive lung fibrosis." (PMID 33119648, 2020). "In conclusion, scutellarin suppressed inflammation and EMT in BLM-induced pulmonary fibrosis through NF-κB/NLRP3 signaling." (PMID 33188176, 2020). "NLRP3 inflammasome activation contributes to mechanical stretch–induced Endo-MT and pulmonary fibrosis." (PMID 33054759, 2020). "While the upstream regulation of NLRP3 inflammasome activation has been well described in lung fibrosis models, the mechanism by which AIM2 inflammasome is activated in lung fibrosis has not been fully elucidated." (PMID 32121297, 2020).
pulmonary fibrosis (continued). "RSV has been found to alleviate lung fibrosis induced by long-term particulate matter (PM) exposure through the inhibition of NLRP3 inflammasome activation and renal fibrosis in mice." (PMID 31717714, 2019). "Collectively, this study demonstrates that exosomal Let-7 from MenSCs remits pulmonary fibrosis through regulating ROS, mtDNA damage, and NLRP3 inflammasome activation." (PMID 31949877, 2019). "Raltegravir ameliorated pulmonary fibrosis by reducing the pathology score, collagen deposition, and expression of α-smooth muscle actin, NLRP3, HMGB1, TLR4, inhibitor of kappa B, p-NF-κB, HIF-1α, collagen I, and collagen III." (PMID 31481891, 2019). "Age-dependent increase in mitochondrial ROS production and NLRP3 inflammasome activation in alveolar macrophages contribute to the development of pulmonary fibrosis." (PMID 31949877, 2019). "Autophagy ameliorated pulmonary fibrosis through suppressing NLRP3 inflammasome activation induced by ROS via redox balance modulation." (PMID 31315822, 2019). "The results of this study demonstrate that RAV attenuated experimental attenuates pulmonary fibrosis by inhibiting NLRP3 activation." (PMID 31481891, 2019). "This study initially explores that LOX1 can promote the apoptosis of alveolar epithelial cells through mtDNA/NLRP3 signal cascades and reverse the protection of lung fibrosis by MenSC-derived exosomal Let-7." (PMID 31949877, 2019). "Enhanced autophagy can inhibit inflammation of macrophages and microglia mediated by NLRP3 inflammasome and alleviate pulmonary fibrosis by inhibiting NLRP3 inflammasome induced by AngII." (PMID 31315822, 2019). "Our previous study showed that the administration of oleanolic acid acetate (OAA) inhibited the activation of the NLRP3 inflammasome and the development of pulmonary fibrosis in PHMG-induced lung injury in mice." (PMID 30087305, 2018). "The results of this study showed that NDN inhibits the inflammatory response and the NLRP3 inflammasome activation of lung fibrosis induced by PHMG." (PMID 30087305, 2018). "A previous study showed that the activation of the NLRP3 inflammasome was observed in BLM-induced lung fibrosis, and NLPR3 deficiency mitigates lung fibrosis." (PMID 30087305, 2018). "On the contrary, currently used chemotherapeutics activate the NLRP3 inflammasome at differential extent in a more unspecific manner and thereby may cause side effects such as cardiotoxicity (anthracyclines), intestinal mucositis (5-fluoruracil), or pulmonary fibrosis (bleomycin)." (PMID 29983861, 2018). "Several published data report NLRP3 as involved in lung fibrosis in both experimental and human samples." (PMID 29675024, 2018). "In the present study, we investigated the effects of NDN on the improvement of pulmonary fibrosis through the regulation of an inflammatory response and the activation of the NLRP3 inflammasome using the PHMG-induced lung fibrosis model." (PMID 30087305, 2018). "Furthemore, our previous studies have demonstrated NLRP3 inflammasome mediated AngII-induced pulmonary fibrosis in animal models." (PMID 29084974, 2017). "In conclusion, our study has demonstrated that AngII induction of mir-21 is a crucial factor that mediates pulmonary fibrosis by activating the NLRP3 inflammasome/IL-1β secretion axis via the Spry1/ERK/NF-κB pathway." (PMID 29084974, 2017). "MicroRNA-21 (mir-21) induced by angiotensin II (AngII) plays a vital role in the development of pulmonary fibrosis, and the NLRP3 inflammasome is known to be involved in fibrogenesis." (PMID 29084974, 2017). "In vivo, AngII exacerbated bleomycin (BLM)-induced lung fibrosis in rats, and elevated mir-21 and the NLRP3 inflammasome." (PMID 29084974, 2017). "Vimentin promotes ALI, alveolar epithelial barrier permeability and lung fibrosis by regulating NLRP3 inflammasome signaling." (PMID 29029603, 2017).
pulmonary fibrosis (continued). "Significantly, both NLRP3- and ASC-deficient mice are protected from silica-induced collagen deposition confirming an important role for the inflammasome in silica-induced lung fibrosis." (PMID 27001429, 2016). "Released cathepsin B from lysosomes to the cytosol will activate NLRP3 inflammasomes to produce IL-1β, which initiate a cascade of events that culminate in pulmonary fibrosis." (PMID 28649460, 2016). "On the other hand, the inflammasome receptor NLRP3, shown to participate in the lung fibrosis induced by uric acid, is activated in kidneys from day-3 p.i. with Leptospira." (PMID 24498450, 2014). "Notably, inhibiting NLRP3 or IL-1β signaling has been shown to slow disease progression and reduce the severity of lung fibrosis by reducing collagen deposition and TGFβ activity." (PMID 40119408, 2025). "This article aims to review the mechanisms of action of NLRP3 in pulmonary fibrosis, related signaling pathways, and the latest research progress on its potential as a therapeutic target, in hopes of providing new ideas and directions for future clinical treatment." (PMID 40391214, 2025). "Notably, a study has reported that the total flavonoid extract (TFE) from Dracocephalum moldavica mitigates pulmonary fibrosis by regulating pyroptosis pathways and autophagy, leading to decreased NLRP3 inflammasome activation." (PMID 39966334, 2025). "The activation of NF-κB not only directly promotes the expression and activation of the NLRP3 inflammasome, but may also be regulated by various cellular stress responses, which play important roles in the occurrence and development of pulmonary fibrosis." (PMID 40391214, 2025). "Moreover, inhibition of the NLRP3 inflammasome has been shown to attenuate the progression of pulmonary fibrosis." (PMID 40391214, 2025). "Therefore, blockade of NLRP3 activation in earlier phases is critical to protect animals against FE-induced pulmonary fibrosis." (PMID 40806699, 2025). "This complete signaling cascade demonstrates the NLRP3 inflammasome as a central node in the pathological process of pulmonary fibrosis, connecting inflammatory responses and fibrotic progression, thus providing a theoretical basis for targeted therapeutic strategies." (PMID 40391214, 2025). "HUMSCs-derived exosomes alleviated silica-induced lung fibrosis via local enhancement of miR-223-3p to repress macrophage-directed nucleotide-binding domain, leucine-rich repeat, and pyrin domain-containing protein 3 (NLRP3)-related inflammation." (PMID 40676634, 2025). "This review systematically summarizes the role and related mechanisms of the NLRP3 inflammasome in pulmonary fibrosis and integrates the latest research progress on NLRP3 inflammasome-targeted therapies in pulmonary fibrosis, hoping to provide new ideas and directions for clinical treatment." (PMID 40391214, 2025). "Likewise, Radix angelica sinensis and Radix astragalus extract have demonstrated the ability to inhibit radiation-induced pulmonary fibrosis by regulating the NLRP3/caspase-1/GSDMD signaling pathway, thereby reducing inflammation and fibrosis markers." (PMID 39966334, 2025). "Notably, the AMPKα/MMP9 axis attenuates skeletal muscle fibrosis, while PPAR-γ/NLRP3/NF-κB signaling mitigates pulmonary fibrosis progression." (PMID 40969268, 2025). "Therefore, nobiletin can be considered a potential molecule in treating pulmonary fibrosis by inhibiting the NLRP3 pathway." (PMID 39966334, 2025). "However, limited studies have shown galangin’s ability to modulate the NLRP3 inflammasome and its anti-inflammatory properties for treating lung fibrosis." (PMID 39966334, 2025). "Subsequent to this, we investigated whether administration of alirocumab or statin could alleviate NLRP3 activity, ultimately ameliorating lung fibrosis in TGF-β1 overexpressing transgenic mice." (PMID 38762465, 2024).